NFKB1 (nuclear factor kappa B subunit 1)
Diseases named in the same sentence as NFKB1 in open-access papers (continued):
Sharing a sentence is not in itself a finding about the gene and the disease.
Parkinson disease (181 papers, 2008 to 2026). A progressive degenerative disorder of the central nervous system characterized by loss of dopamine producing neurons in the substantia nigra and the presence of Lewy bodies in the substantia nigra and locus coeruleus. "In Parkinson's disease, it has been reported that polymorphisms in the NFKB1 gene may affect the development of redox balance to prooxidation framework and may help regulate disease progression." (PMID 34721758, 2021). "Significantly reduced NFKB1 expression has been observed in Parkinson’s disease patient samples, and NFKB1 knockout (NFKB1−/−) mice exhibit exacerbated microglial activation and dopaminergic neuron loss." (PMID 41465406, 2025). "Egr1 (early growth response 1) and Nfkb1 (nuclear factor-κb subunit 1) induce the transcription of pro-inflammatory cytokines, and EGR1 activation promotes neuroinflammation and degeneration in experimental Parkinson's disease." (PMID 35529318, 2022).
neuroblastoma (177 papers, 2007 to 2026). Neuroblastoma (NB) is the most common solid, extracranial childhood tumor. "Indeed, compared with neuroblastoma, in Ewing sarcoma cDCs showed significantly lower expression of NFKB1 and STAT3, confirming their dysfunctional state and involving previously reported signaling pathways in the observed phenotype." (PMID 37823774, 2023).
systemic lupus erythematosus (167 papers, 2009 to 2026). An autoimmune multi-organ disease typically associated with vasculopathy and autoantibody production. "The NFKB1-94ins/del ATTG polymorphism produces lower protein levels of p50, having been reported to correlate with many inflammatory diseases such as Grave’s disease, ulcerative colitis, and systemic lupus erythematosus." (PMID 26075620, 2015).
diffuse large B-cell lymphoma (163 papers, 2010 to 2025). "In malignancy processes, it was noted that the activation of either NFKB1 or NFKB2 is associated with different phenotypes of cancer, namely in diffuse large B-cell lymphoma (DLBCL)." (PMID 36555871, 2022).
metabolic syndrome (161 papers, 2010 to 2026). A cluster of metabolic risk factors for CARDIOVASCULAR DISEASES and TYPE 2 DIABETES MELLITUS. "Thus, herein, we constructed a mRNAs (DDX58, NFκB1& CHUK)—(miR-1976) panel linked to metabolic syndrome and pancreatic cell dysfunction as well as be enrolled in the cGAS-STING pathway via in silico data analysis." (PMID 36915161, 2023). "In contrast, HFD+CHOL caused macrovesicular steatosis, inflammation, early fibrosis, atherogenic dyslipidemia, intrahepatic cholesterol accumulation, hepatocyte apoptosis, upregulated Srebf1, Cyp7a1, and Nfkb1 expression, and activated Nrf2-dependent antioxidant responses." (PMID 42196216, 2026).
heart failure (158 papers, 2009 to 2025). Inability of the heart to pump blood at an adequate rate to meet tissue metabolic requirements. "By using Cytoscape software (Version: 3.10.2) in conjunction with MCC algorithms of the CytoHubba plugin, we identified the top 5 hub genes within the network (IL1B, NFKB1, MAP2K1, PRKACA, and HSP90AA1), suggesting that these genes are potential targets for EMPA and MET in heart failure therapy." (PMID 40364820, 2025).
endometriosis (153 papers, 2006 to 2026). The growth of functional endometrial tissue in anatomic sites outside the uterine body. "SNP rs28362491 in promoter sites of NFKB1 has been reported to have a positive association with both moderate and severe endometriosis caused infertility, and idiopathic female infertility." (PMID 29942932, 2018). "Recently, it has been suggested that CYP17, VDR, MUC17, COX-2, WNT4, E-cadherin, CYP19, CYP17, TYK2, NFKB1, and MUC2 gene variants also contributed to endometriosis-related infertility." (PMID 28405865, 2017).
liver diseases (145 papers, 2011 to 2026). "Whole exome sequencing (WES) was conducted by next-generation sequencing (NGS) in all 11 patients suffering from portal hypertension (CVID+PH), revealing a pathogenic mutation for NFKB1 in patient #3 and CTLA4 haploinsufficiency in patient #10." (PMID 38187397, 2023). "We also describe the clinical features of liver disease in some monogenic forms of PID included in the clinical spectrum of CVID as ICOS, NFKB1, NFKB2, CTLA-4, PI3Kδ pathway, ADA2, and IL21-R genetic defects." (PMID 32184784, 2020).
acute myeloid leukemia (143 papers, 2007 to 2026). Acute myeloid leukemia (AML) is a group of neoplasms arising from precursor cells committed to the myeloid cell-line differentiation. "mRNA expression analysis has revealed that NFKB1 is downregulated in multiple human haematological malignancies, including T and B-cell lymphoma and acute myeloid leukemia, while p65 expression is upregulated." (PMID 30205516, 2018).
breast tumor (136 papers, 2006 to 2025). "Increased expression of p50/NFκB1, p52/NFκB2, and c-Rel was detected in breast tumors compared to adjacent normal tissue." (PMID 31178825, 2019). "Over-expression of NFκB subunits NFκB3 and NFκB1 were found in a high percentage of breast tumours and are inversely correlated with ER-status, which is in agreement with our findings." (PMID 19826428, 2009). "Additionally, increased p50/NFκB1, p52/NFκB2, and cRel expression were observed in breast tumors compared with normal surrounding tissues." (PMID 36045911, 2022). "BAX, BCL2, NFKB1 and ABCG2 genes expression were compared by using breast tumor tissues on TCGA-BRCA." (PMID 41154846, 2025).
Anxiety (132 papers, 2012 to 2026). Intense feelings of nervousness, tension, or panic often arise in response to interpersonal stresses. "In a previous study on female rats exposed to 10 weeks of HFD containing 60% fat, HFD increased anxiety-like behavior and decreased the expression of NFκB1, as well as the expression of glucocorticoid receptors (GRs) in the hippocampus, compared to rats fed a low-fat diet containing 10% fat." (PMID 40558565, 2025).
oral cancer (131 papers, 2007 to 2026). "The results indicated that NFKB1 rs28362491 Del/Del and rs72696119 G/G genotypes were associated with the risk of oral cancer, with a strong linkage disequilibrium (D′ = 0.991, r2 = 0.971)." (PMID 29635862, 2018). "NFKB1 rs28362491 Del/Del genotype was associated with a 1.57‐fold increased risk of oral cancer (adjusted OR = 1.57, 95% CI: 1.07–1.92, P = 0.030)." (PMID 29635862, 2018). "Accordingly, we evaluated the combined effect of environmental carcinogens and NFKB1 gene polymorphisms on the risk of oral cancer." (PMID 22509384, 2012). "Our preliminary findings suggest that the haplotype of rs28362491 and rs72696119 in NFKB1 could act as a novel genetic marker to predict oral cancer risk in the southeast of China, but much more extensive researches still need to be conducted." (PMID 29635862, 2018). "Moreover, DG haplotype of NFKB1 had a 1.25‐fold risk of developing oral cancer compared with IC haplotype." (PMID 29635862, 2018). "Moreover, limited experimental studies have been conducted to explore the biological mechanism of NFKB1 polymorphisms on susceptibility of oral cancer." (PMID 29635862, 2018). "Our study could provide an additional evidence for the function of NFKB1 gene on oral cancer risk, and help understand the molecular mechanisms of oral cancer." (PMID 29635862, 2018). "In conclusion, this preliminary study demonstrates that the haplotype of rs28362491 and rs72696119 in NFKB1 could act as novel genetic markers to predict the risk of oral cancer in the southeast of China." (PMID 29635862, 2018). "We further explored the mechanism by which the DG haplotype was found to reduce the transcription activity of NFKB1, which may provide a possible explanation for rs72696119 polymorphism in the etiology of oral cancer." (PMID 29635862, 2018). "Moreover, we found that NFKB1 or NFKBIA gene polymorphisms seem to be related to susceptibility to develop oral cancer linked to betel nut and tobacco consumption." (PMID 22509384, 2012). "Among betel nut consumers in the cohort, tobacco smoking elevated oral cancer risk significantly in participants polymorphic for NFKB1 in the −94 locus or NFKBIA in three loci (−519, −826, and −881), compared with people with the WT gene who did not smoke tobacco." (PMID 22509384, 2012). "Moreover, Chen F reported that the -94delATTG allele promoter of NFKB1 abolished the binding site of transcription factor and it may increase the susceptibility to oral cancer." (PMID 30910844, 2019). "Haplotype analyses of NFKB1 gene demonstrated that IC was the most frequent haplotypes (52.64% for cases and 57.41% for controls), and DG haplotype carriers had a significantly increased risk of oral cancer than subjects with IC haplotype (adjusted OR = 1.25, 95% CI: 1.02–1.53, P = 0.030)." (PMID 29635862, 2018). "In conclusion, our results suggest that NFKB1 gene polymorphisms might be correlated with oral cancer susceptibility, and the combined effect of NFKB1 or NFKBIA gene polymorphisms with environmental carcinogens increases risk of oral cancer development significantly." (PMID 22509384, 2012). "Thus, increased risk for oral cancer associated with the NFKB1 ATGG1/ATGG2 variant might have resulted from its positive regulation of NF-κB expression." (PMID 22509384, 2012). "The purpose of this study was to evaluate the associations of polymorphisms in NFKB1 and NFKBIA with oral cancer susceptibility, and further explore their potential mechanism in vitro." (PMID 29635862, 2018). "First, the polymorphisms of NFKB1 and NFKBIA were genotyped through iPLEX Sequenom MassARRAY platform in a case–control study with 425 oral cancer patients and 485 healthy controls." (PMID 29635862, 2018). "The combination of polymorphism of nuclear factor kappa B1 (NFKB1) -94 ATTG, NFKBIA -826 T,-881 G alleles and environmental carcinogen were associated with increasing risk of betel-quid related oral cancer." (PMID 28404909, 2017).
oral cancer (continued). "The combination of NFKB1 or NFKBIA gene polymorphisms and environmental carcinogens appears related to an increased risk of oral cancer." (PMID 22509384, 2012). "The current study investigated relationships between SNPs in the promoter regions of the NFKB1 and NFKBIA genes and the risk of oral cancer." (PMID 22509384, 2012). "Therefore, this study aims to examine the association of NFKB1 and NFKBIA genes polymorphisms with the susceptibility to oral cancer in southeast China, and further explore their biological mechanism on oral cancer in vitro." (PMID 29635862, 2018). "Genetic polymorphisms of NFKB1 and NFKBIA were analyzed by a real-time polymerase chain reaction (real-time PCR) for 462 patients with oral cancer and 520 non-cancer controls." (PMID 22509384, 2012).
triple-negative breast carcinoma (130 papers, 2009 to 2026). An invasive breast carcinoma which is negative for expression of estrogen receptor (ER), progesterone receptor (PR), and human epidermal growth factor receptor 2 (HER2). "The MDA-MB-231 triple-negative breast cancer cells (TNBC) investigated during parabolic flight maneuvers showed an early upregulation of ICAM1, CD44, and ERK1 mRNAs and a delayed upregulation of NFKB1, NFKB p-65, and annexin-A2 protein." (PMID 35328492, 2022).
B-cell lymphoma (126 papers, 2004 to 2026). "And indeed, loss of Nfkb2 gene accelerated B cell lymphoma (BCL) development in Eμ-MYC tg mice, whereas the Nfkb1 gene was shown to be dispensable for MYC-induced lymphomagenesis, and overall NF-κB and Calcineurin (CN)–dependent NFATc2 activation induced apoptosis in human BL cells." (PMID 37546418, 2023).
steatosis (120 papers, 2008 to 2026). Increased lipid within the cytoplasm of cells. "For the “oxidative stress” pathway, two genes (NFκB1 and MTX1) were lower in steatosis compared to HOC." (PMID 34869521, 2021).
dermatitis (109 papers, 2007 to 2026). An inflammatory process affecting the skin. "Our study revealed very high frequencies (up to 95%) of chestnut horses harboring NFKB1, SLC39A8, BANK1 and UVSSA in ROH islands, and indicated evidence that these genes may be involved in the reported higher susceptibility of chestnut horses for skin disorders." (PMID 31261764, 2019).
chronic kidney disease (103 papers, 2011 to 2026). Impairment of the renal function secondary to chronic kidney damage persisting for three or more months. "We used data from a large genome-wide association study to examine whether common SNPs in any of the genes encoding the kidney aging transcription factors (STAT1, STAT3 and the canonical NFκB complex genes RELA and NFKB1) show an association with kidney function or chronic kidney disease." (PMID 26678048, 2015). "We found two independent DNA variants in the NFκB transcription factor genes RELA and NFKB1 (rs11820062 and rs12509403, respectively) that associate with kidney function and chronic kidney disease susceptibility in the human population." (PMID 26678048, 2015). "Nrp1 interacts with both TGF-β and TNF-α receptors in distal TECs while activating the Nfkb1 and Smad3 pathway, regulating the secretion of collagen, suppressing OXPHOS, activating myofibroblasts, thereby accelerating the progression of acute and chronic kidney diseases." (PMID 38977708, 2024).
atopic dermatitis (102 papers, 2007 to 2026). "There were 28 core targets related to UVB-induced allergic dermatitis, of which hub proteins were TNF-α, NFKB1, MMP-9, and IL-2." (PMID 40232010, 2025).
gout (101 papers, 2012 to 2026). A condition characterized by painful swelling of the joints, which is caused by deposition of urate crystals. "The results showed that key transcription factors such as CEBPB, STAT3, RELA, and NFKB1 may be involved in the pathogenesis of gout by directly regulating the transcriptional levels of these genes." (PMID 40606658, 2025). "RELA and NFKB1 are the core components of the classic NF-κB signaling pathway, directly involved in the regulation of various pro-inflammatory genes (such as CXCL8 and PTGS2), driving gout-related inflammatory responses." (PMID 40606658, 2025). "Candidate targets of turmeric for gout were HSPA8, VCP, HSP90AB1, HSPA5, HSPA1B, NFKB1, and STUB1." (PMID 36276864, 2022).
thyroid cancer (101 papers, 2009 to 2025). "In summary, while RELA and NFKB1 have been shown to play a role in the development of various types of cancer, their specific function in thyroid cancer development remains unclear." (PMID 37954148, 2023). "Although RELA and NFKB1 have not been directly linked to the development of thyroid cancer, the protein has been implicated in the development of other types of cancer." (PMID 37954148, 2023).
multiple sclerosis (100 papers, 2010 to 2025). A progressive autoimmune disorder affecting the central nervous system resulting in demyelination. "Higher production of proinflammatory TNFα and susceptibility to multiple sclerosis is also associated with some genetic variants in the NF-κB signaling cascade, such as variants proximal to NFκB1 and in an intron of TNFRSF1A (TNFR1), which leads to higher NF-κB signaling after stimulation with TNFα." (PMID 33271810, 2020).
type 1 diabetes (97 papers, 2009 to 2025). "Notably, in vivo experiments using AD-1 in streptozotocin-induced type 1 diabetic mice confirmed its therapeutic efficacy, significantly downregulating key diabetic markers (e.g., NFKB1 and HDAC1) in pancreatic tissues—a finding unreported in prior studies." (PMID 40508108, 2025). "Elevated NFKB1 mRNA expression was attributable to the development of pro-inflammatory status in children and adolescents with type 1 diabetes, which might eventually result in deterioration in renal function and, ultimately, DKD." (PMID 36035169, 2022).
influenza (92 papers, 2010 to 2026). An acute viral infection of the respiratory tract, occurring in isolated cases, in epidemics, or in pandemics; it is caused by serologically different strains of viruses (influenzaviruses) designated A, B, and C, has a 3-day incubation period, and usually lasts for 3 to 10 days. "The F15 NOD Nfκb1 heterozygote and homozygote mice were found to have an increased risk of myocarditis after influenza or HBV vaccination." (PMID 35740465, 2022). "However, there have been rare studies on the genetic variations of the NFκB1 gene and the importance of these genetic variants in contributing to the severity of the influenza disease." (PMID 36296162, 2022). "The results of these immune system experiments indicate that inoculating F15-NOD Nfκb1 heterozygote mice with influenza or HBV vaccine may cause myocarditis." (PMID 35740465, 2022). "In 129P2 (B6) wild-type and 129P2 (B6) Nfκb1 heterozygote mice, the cTnT level after influenza or HBV vaccination was below the standard (0.014 ng/mL) with no gender difference." (PMID 35740465, 2022). "Targeting the NFkB1 expression may prevent dysregulation of multiple cytokines and/or chemokines in patients with severe response to future influenza infections." (PMID 36296162, 2022). "Our findings showed that sequence variations of the NFκB1 gene might influence patient response to influenza infection." (PMID 36296162, 2022). "In NOD/ShiLtj and F15 NOD Nfκb1 wild-type mice, the median cTnT level for PBS, influenza vaccine, or HBV vaccine ranged from 0.012 to 0.014 ng/mL." (PMID 35740465, 2022). "Therefore, we conducted histopathological studies in NOD/ShiLtj, Nfκb1 genetically modified 129P2 (B6), and F15-NOD mice to investigate myocarditis development after inoculation with influenza vaccine (influenza HA vaccine “KMB”) or HBV vaccine (Bimmugen)." (PMID 35740465, 2022). "In F15 NOD Nfκb1 heterozygote mice, an increase in cTnT level (>0.02 ng/mL) after influenza or HBV vaccination was detected with no gender difference." (PMID 35740465, 2022). "Additionally, we investigated cTnT, which is a marker for myocarditis, after the inoculation of influenza or HBV vaccine in NOD/ShiLtj, Nfκb1 genetically modified 129P2 (B6), and F15-NOD mice." (PMID 35740465, 2022). "Additionally, in NOD Nfκb1 heterozygote mice, myocarditis with an increase in cTnT levels due to influenza or hepatitis B virus vaccination was observed with no significant gender difference." (PMID 35740465, 2022). "Additionally, in NOD Nfκb1 heterozygote mice, myocarditis with an increase in cTnT levels due to influenza or HBV vaccination was observed with no significant gender difference." (PMID 35740465, 2022).
chronic lymphocytic leukemia (86 papers, 2010 to 2025). "Therefore, NFKB1 could be directly linked to B cell proliferation in chronic lymphocytic leukemia, characterised by an abnormally increased level of B cells in the lymph nodes, bone marrow, and blood." (PMID 30205516, 2018).
allergic disease (78 papers, 2005 to 2026). An immune response that occurs following re-exposure to an innocuous antigen, and that requires the presence of existing antibodies against that antigen. "The observed inverse effect in allergy compared with infection and inflammatory disease may be a result of impaired resolution of inflammation stemming from a dysregulation of NFKB1 expression as a result of disrupted promoter binding." (PMID 38232728, 2024).